PLK1 (polo like kinase 1)
Diseases named in the same sentence as PLK1 in open-access papers (continued):
Sharing a sentence is not in itself a finding about the gene and the disease.
gastrointestinal tumor (3 papers, 2014 to 2022). "PBK, AURKB, KIF11, and PLK1 confirmed that they are closely related to the occurrence and progression of gastrointestinal tumors, including HCC." (PMID 34200261, 2021).
neurodegenerative disease (3 papers, 2017 to 2025). A disorder of the central nervous system characterized by gradual and progressive loss of neural tissue and neurologic function. "Outside of its’ traditional function, PLK-1 regulates various events, including DNA replication, transcription, translation, chromosomes dynamics, DNA damage response (DDR), checkpoint adaptation and recovery, neurodegenerative diseases, apoptosis, organogenesis, so on." (PMID 28415805, 2017).
colorectal (2 papers, 2014 to 2024). "MAP9 downregulation is associated with colorectal malignancy and could be used as a disease marker and a new drug target, while AURKA and PLK1 are upregulated." (PMID 24876664, 2014). "In fact, analysis of PLK1-depletion in CRC cells cultures and CRC mice models demonstrate a key role for PLK1 in colorectal carcinogenesis." (PMID 39273409, 2024).
respiratory disease (1 paper, 2011). "A subset of genes co-expressed with AQP4 and associated to respiratory disease were assigned to potential anti-tumorigenic function like CAV1, EDNRB, or SELENBP1, whereas genes more related to pro-tumorigenic function like CDK2, FOXM1, PLK1 or RRM1 were found to be anti-correlated with AQP4." (PMID 21548930, 2011).
PLK1 also shares sentences with these, for which no sentence is quoted: metastatic melanoma (4 papers); acute lymphoblastic leukemia (2); benign breast tumors (2); benign prostatic hyperplasia (2); colon adenocarcinoma (2); COVID-19 (2); fibrosis (2); Hyperglycemia (2); influenza (2); mantle cell lymphoma (2); metabolic disorders (2); papillary carcinoma (2); rectum adenocarcinoma (2); synovial sarcoma (2); thymoma (2); tongue squamous cell carcinoma (2); acinar cell carcinoma (1); actinic keratosis (1); Acute Monoblastic Leukaemia (1); adrenocortical tumour (1); benign tumors (1); brain glioma (1); Burkitt lymphoma (1); carcinoma in situ (1); cardiovascular disease (1); cervical small cell carcinoma (1); cervix (1); Chlamydia infection (1); chronic hepatitis B (1); CNS tumors (1).
A further 61 diseases each share a sentence with PLK1 in 1 paper.